MMP9 (matrix metallopeptidase 9)
Diseases named in the same sentence as MMP9 in open-access papers (continued):
Sharing a sentence is not in itself a finding about the gene and the disease.
emphysema (continued). "MMP-1 and MMP-9, major members of MMPs, contribute to the development of cigarette-induced emphysema." (PMID 23555986, 2013). "Upper lung-dominant emphysema is associated with genetic variants in MMP-9 or EPHX1 and GSTP1 and the cranial-caudal emphysema distribution is a powerful predictor of the response to lung volume reduction surgery." (PMID 22512922, 2012). "Previous studies have shown that variants of MMP-9 or EPHX1 and GSTP1 are associated with upper-predominant emphysema." (PMID 22512922, 2012). "IL-17A can also induce the release of matrix metalloproteinase (MMP)-9, which is involved in emphysema." (PMID 22032685, 2011). "MMP-8 and MMP-9 are two proteases that are believed to play an important role in the tissue destruction that results in emphysema and both are raised in COPD subjects in the biomarker cohort." (PMID 22054035, 2011). "Quercetin prevents progression of emphysema in elastase/LPS-treated mice by reducing oxidative stress, lung inflammation and expression of MMP9 and MMP12." (PMID 20920189, 2010). "A similar role of MMP-9 has been reported that transgenic MMP-9 expression induces adult-onset emphysema in mice." (PMID 19706153, 2009). "HSP60 also induces matrix metalloproteinases (MMPs) production by macrophages, particularly of MMP-9, an enzyme are felt to be involved in the pathogenesis of emphysema." (PMID 18021431, 2007). "Elevated protein levels of MMP-1, MMP-8 and MMP-9 were found in BALF or lung parenchyma of patients with emphysema." (PMID 16316467, 2005). "Previous studies have related MMP-9 to parenchymal destruction and lung function decline, in sub clinical and established emphysema." (PMID 16372907, 2005). "Moreover, Macro_SPP1 cells showed elevated expression of protease genes (e.g., ADAM9, CTSL, CTSS, and MMP9) in COPD, which were associated with emphysema and airway remodeling." (PMID 40589761, 2025). "An imbalanced MMP-9/TIMP-1 ratio is an important determinant in the pathogenesis of emphysema." (PMID 38790616, 2024). "An investigation of genetic polymorphisms in MMP-9 and TGF-β1 genes found that the T allele frequency in the promoter of MMP-9 (C-1562T) was higher in CPFE than in IPF patients and comparable to that observed in the emphysema group." (PMID 37174678, 2023). "Specifically, by decreasing antioxidant defenses, HIV proteins promote MMP-9 activity, which could subsequently prime the lung for the development of emphysema." (PMID 36331810, 2023). "To assess the relationship between HIV, MMP-9, and emphysema, we first made use of the HIV transgenic rat model to determine whether HIV proteins are sufficient to increase the risk for emphysema." (PMID 36331810, 2023). "In addition, we plan to investigate emphysema outcomes in the setting of MMP-9 inhibition in this HIV rat model to cement the role of MMP-9 in the disease pathway." (PMID 36331810, 2023). "In summary, in determining a role for MMP-9 and antioxidant defenses in HIV-associated emphysema, we believe these data set the stage for future studies of host-directed therapies, particularly therapies designed to attenuate HIV-associated oxidative stress to diminish MMP-9 activity." (PMID 36331810, 2023). "Given the known effects of MMP-9 in emphysema and prior data from human subjects suggesting elevated levels in the setting of HIV, we next treated a rat alveolar macrophage cell line (NR8383) with the HIV protein transactivator of transcription (Tat) to determine its effects on MMP-9." (PMID 36331810, 2023). "Moreover, by upregulating MMP-9 and inactivating α1-antitrypsin, it decreases the elasticity of lungs, thus leading to emphysema, which is an irreversible condition." (PMID 35784687, 2022). "Moreover, it can improve emphysema (emphysema index D2, levels of MMP-9 in bronchoalveolar lavage fluid (BALF), and the expression of α-1 antitrypsin) and prevent impairments of lung function (e.g., PEF, intratracheal pressure (IP), and IP-slope)." (PMID 35745833, 2022).
emphysema (continued). "Further, we found that genetic deletion of NE, but not Mmp9 improves lung function impairment associated with emphysema-like structural lung damage in βENaC-Tg mice." (PMID 36362203, 2022). "Third, we demonstrate by complementary analyses including morphometry of lung tissue and pulmonary function testing that MMP-9 is not implicated in the development of emphysema-like structural lung damage in βENaC-Tg mice." (PMID 36362203, 2022). "Our data show that MMP-9 deficiency does not ameliorate the emphysema phenotype of βENaC-Tg mice, which is characterized by an increased lung volume, distal airspaces enlargement and destruction of alveolar septa on histology." (PMID 36362203, 2022). "Long-term smoke causes chronic airway inflammation in patients with COPD, stimulating airway mucosa to produce TGF-β and MMP-9, which leads to protease/anti-protease imbalance, alveoli destruction, hydrolyzed alveolar elastic fibers, alveolar fusion, and finally emphysema." (PMID 35774607, 2022). "MMP-1, MMP-9 and MMP-12 are mainly implicated in emphysema pathogenesis." (PMID 33435568, 2021). "Notably, a previous report demonstrated that inhibition of MMP-9/MMP-12 considerably suppresses emphysema morphology and small airway remodeling." (PMID 34784929, 2021). "Thus, the expression of factors associated with tissue destruction and healing, including MMP-12, MMP-9, and Cathepsin S, was also increased in emphysema mice." (PMID 32681029, 2020). "FEV1 was correlated with MMP-9/TIMP-1 imbalance in patients with emphysema (r = 0.664, p < 0.001)." (PMID 30781876, 2019). "Recently, a study showed that the expression of MMP-9 along with NF-κB was increased in CS extract stimulated peripheral blood mononuclear cells (PBMCs) and murine alveolar macrophage cells and in a CS-induced emphysema rat model." (PMID 30298007, 2018). "Mice were also protected from the Al2O3 NPs-induced inury markers previously shown to be associated with emphysema, with levels of matrix metalloproteinase 9 (MMP9) being indistinguishable from those in mice exposed to filtered room air (FRA)." (PMID 29233151, 2017). "MMP-9 and NE contribute to emphysema through the destruction of the lung parenchyma." (PMID 27184092, 2016). "Other clinical manifestations of COPD to which MMP-9 may be of importance in the pathogenesis are emphysema and rapid decline in lung function." (PMID 25849664, 2015). "In emphysema, the expression of MMP-9 and MMP-12 is increased." (PMID 26122092, 2015). "It has previously been suggested that MMP-9 is related to the development of emphysema." (PMID 25849664, 2015). "Increased MMP-1 and MMP-9 levels have been detected in BALF of emphysema patients." (PMID 26770019, 2015). "There is an increase in activity of MMP-9 in the lung parenchyma of patients with emphysema." (PMID 25309536, 2014). "Interestingly, prostacyclin treatment attenuated MMP-9 synthesis in mesangial cells and in an animal model of cigarette smoke induced emphysema." (PMID 23406566, 2013). "The findings of an association of greater MMP-9 expression in moderate to severe disease with greater airflow obstruction and reduced diffusing capacity as well as more extensive emphysema on CT scanning with MMP-9 concentrations suggests a role for MMP-9 in the pathogenesis of emphysema." (PMID 27234393, 2013). "Furthermore, several polymorphisms in MMP1, MMP9, and MMP12 genes have been associated to emphysema and related phenotypes." (PMID 23734748, 2013). "Alternatively, increased sputum MMP-9 may be a marker of disease severity in patients who already have emphysema." (PMID 27234393, 2013). "Both preventive and therapeutic NAC administration did not affect or reverse the development of ozone-induced emphysema and this was associated with the failure to inhibit caspase-3 or MMP-9 expression." (PMID 24260479, 2013).
emphysema (continued). "The ex-smokers with COPD in the present study had more severe disease, as assessed by the extent of emphysema on CT, which may explain the higher sputum MMP-9 concentrations in this group." (PMID 27234393, 2013). "Indeed, circulating monocytes of advanced emphysema subjects have the highest levels of MMP-9 production and the expression of this protease in alveolar macrophages causes progressive adult-onset emphysema in mice." (PMID 23441181, 2013). "Long-term clinical trials of MMP-9 inhibitors in COPD would help establish whether blocking MMP-9 activity attenuates the development and progression of emphysema." (PMID 27234393, 2013). "The severity of COPD, when assessed by the extent of emphysema on CT scanning, but not by spirometry values, was significantly associated with sputum MMP-9 concentrations and activity." (PMID 27234393, 2013). "Overall, this study supports prior research indicating MMP-9 may be a valuable biomarker for the progression of emphysema." (PMID 21429222, 2011). "Utilizing data from the placebo arm of a clinical trial, we tested the hypotheses that plasma MMP-9 levels are cross-sectionally and prospectively associated with pulmonary status declines and with COPD exacerbations among emphysema patients with AATD." (PMID 21429222, 2011). "Matrix metalloproteinase-9 (MMP-9) may be important in the progression of emphysema, but there have been few longitudinal clinical studies of MMP-9 including pulmonary status and COPD exacerbation outcomes." (PMID 21429222, 2011). "Our study was not designed to establish a causative role of MMP-9 in antitrypsin deficient emphysema progression." (PMID 21429222, 2011). "Increased plasma MMP-9 levels generally predicted pulmonary status declines, including worsening transfer factor and lung density as well as greater COPD exacerbations in AATD-associated emphysema." (PMID 21429222, 2011). "MMP-8 (r = 0.15, p = 0.043), MMP-9 (r = 0.18, p = 0.011) and adiponectin (r = 0.26, p =< 0.001) also correlated weakly with the percentage of emphysema as defined by low attenuation area on chest CT scans; MMP-9 correlated with the radiologists' score of emphysema (r = 0.18, p = 0.010)." (PMID 22054035, 2011). "We hypothesized that in the long-term smoke-induced mouse model double-stranded ODNs decoy to NF-κB would suppress the pulmonary expression levels of inflammation-related genes and MMP-9/TIMP-1 gene that may play a role in the development of emphysema." (PMID 19706153, 2009). "It has been shown that an MMP-9/MMP-12 inhibitor can substantially ameliorate morphological emphysema in guinea pigs, suggesting that MMPs may be important mediators of the anatomical changes behind COPD." (PMID 19014449, 2008). "More recent investigations provide evidence that both, elastase activities, such as MMP-12, and collagenolytic activities, as exerted by MMP-2 and MMP-9, in combination lead to an effective destruction of lung parenchymal tissue that finally results in the generation of emphysema." (PMID 16398938, 2006). "Our results suggest that MMP9 may be regulated at the protein level in emphysema." (PMID 29476075, 2018). "However, a definitive role of MMP-9 in the development of emphysema is uncertain." (PMID 27234393, 2013). "Thus, our data indicating an increase in MMP-9: TIMP-1 ratio in vitamin D deficient smoke-exposed mice provides a mechanism whereby vitamin D deficiency can influence and accelerate the development of emphysema." (PMID 23781205, 2013). "Previously, we reported that sputum MMP-12 concentrations and activity in patients with COPD are directly associated with the extent of emphysema measured by CT suggesting that blocking both MMP-9 and MMP-12 may be more effective than inhibiting either MMP-9 or MMP-12 alone." (PMID 27234393, 2013). "Elevated levels of MMP-9 have been documented in the vasculature during ACS, as well as in diverse pathologies such as emphysema, arthritis, and certain progressive tumors." (PMID 40224343, 2025).
emphysema (continued). "Oxidative stress increases the expression of matrix metallopeptidase 9 (MMP9), an elastolytic enzyme, related to the development of emphysema." (PMID 36671004, 2023). "This family of enzymes is recognized as a key factor in lung ECM turnover and the members of the family, including MMP-9 and MMP-12, seem to be involved in an imbalance in protease and antiprotease activity, leading to the development of emphysema." (PMID 36767357, 2023). "While MMP-9 is generally believed to be a key player of ECM remodeling, reports are conflicting regarding its role in emphysema development." (PMID 36362203, 2022). "Neutrophils recruited to the lung secrete proteolytic enzyme, ROS, matrix metalloproteinase-9 (MMP-9), and MMP-12, leading to mucus hypersecretion and emphysema." (PMID 35326218, 2022). "Another study using IL-13 overexpression in transgenic (TG) mice described the induction of MMP-2, MMP-9, MMP-12, MMP-13, and MMP-14; cathepsins such as B, S, L, H, and K, involved in emphysema development and increased lung inflammation." (PMID 35740358, 2022). "A higher IL-17 expression correlates with higher MMP-12 mRNA expression, which plays a significant role in the formation of emphysema; a stimulation of the IL-17 → MCP-1(Ccl-2) → MMP-9 → MMP-12 axis is crucial." (PMID 36293561, 2022). "Oxidative stress increases the expression of matrix metallopeptidase 9 (MMP-9), a key enzyme with elastolytic activity involved in the origin of emphysema." (PMID 35453648, 2022). "Similar conclusions were reported previously indicating that the mechanisms of emphysema include activation of macrophages by LPS release and elastolytic enzymes (proteinase), mainly MMP-2, MMP-9, MMP-12, and cytokines from chemotactic neutrophils." (PMID 34136063, 2021). "Considering a biochemical study demonstrating that NGAL prevented matrix metalloproteinase (MMP)- 9 from being degraded and maintained the MMP-9 enzymatic activity, NGAL has been recognized to contribute to the development of pulmonary emphysema." (PMID 34064650, 2021). "Macrophages, epithelial cells, and infiltrated inflammatory cells release, on the one hand, proteases such as matrix metalloproteinase 9 (MMP9), resulting in elastin degradation and emphysema." (PMID 33297418, 2020). "This and other studies have suggested that the MMP-9 concentration and the MMP-9/TIMP-1 ratio are the best predictors of emphysema in COPD patients." (PMID 33419373, 2020). "Various nuclear receptor agonists were reported to control neutrophil accumulation and the expression of MMP-9, and agonists of PPARγ and LXR exerted some anti-neutrophilic inflammatory and protective effects in the development of emphysema in a murine model." (PMID 30606200, 2019). "MMP-9 concentration and the MMP-9/TIMP-1 ratio were higher in patients with emphysema than in other phenotypes (both with p < 0.01)." (PMID 30781876, 2019). "MMP-9 concentration and the MMP-9/TIMP-1 ratio were higher in patients with emphysema than in other phenotypes, and FEV1 was correlated with MMP-9/TIMP-1 imbalance." (PMID 30781876, 2019). "Our results are in agreement with observations that MMP9 can alter ECM and induce progressive airspace enlargement leading to emphysema development." (PMID 29476075, 2018). "In the early onset of emphysema/COPD mice had increased influx of inflammatory cells and upregulation of MMPs, such as MMP-2, MMP-9, and MMP-12 in the lung." (PMID 30402133, 2018). "In an animal model of emphysema and in patients with COPD, several MMPs, including MMP-9, are elevated in sputum, BALF, and lung tissue specimens and are related to poor lung function." (PMID 28704475, 2017). "It has been shown that in patients with emphysema, there is elevated concentration of MMP-1 and MMP-9 in BAL and increased expression of these MMPs in macrophages." (PMID 26126526, 2015).
emphysema (continued). "Some authors have suggested that MMP-9 and MMP-12 are relevant to emphysema, are involved in experimental models of elastase, and are involved in the degradation of collagen fibers." (PMID 26122092, 2015). "One recent study has shown the role of MMP9 and MMP2 in emphysema secondary to wood smoke (WS) exposure in a guinea pig model." (PMID 24802298, 2014). "Patients with emphysema have an increase in BALF concentrations and macrophage expression of MMP-1, MMP-2 and MMP-9 and activity of MMP-9 in the lung parenchyma." (PMID 24144354, 2014). "The decrease in plasma MMP-9 and TIMP-1 levels that were measured in the emphysema cohort contrasted with a recent study that showed that serum levels of these proteins were elevated in COPD." (PMID 23441181, 2013). "The collagenase MMP-1, the gelatinase MMP-9 and the metalloelastase MMP-12 are of particular interest in emphysema pathogenesis." (PMID 23441181, 2013). "In contrast to BALF, plasma MMP-9 and TIMP-1 levels were actually decreased in the emphysema cohort compared to the control groups." (PMID 23441181, 2013). "The pro-inflammatory cytokine IFN-gamma is a potent stimulator of MMP-9 and CCR5 ligands, the expression of which ultimately results in DNA damage, apoptosis, and emphysema." (PMID 23450717, 2013). "In patients with emphysema there is an increase in BALF concentrations and macrophage expression of MMP-9." (PMID 22412999, 2012). "Finally, clinical studies thus far have not reported on the longitudinal associations between MMP-9 and outcomes within the context of AATD-associated emphysema, a phenotype of COPD that could be particularly relevant to understanding the role of MMP-9 in the natural history of COPD pathogenesis." (PMID 21429222, 2011). "MMPs, particularly increased levels of MMP-9 and MMP-12, are involved in CS-mediated airspace enlargement/alveolar wall destruction (emphysema)." (PMID 20663150, 2010). "Release of MMPs is also crucial for tissue destruction by macrophages in human emphysema and increased activities of MMP-8 and MMP-9 are found in induced sputum of humans with COPD." (PMID 18230187, 2008). "Destruction of lung parenchyma in emphysema is thought to occur through excessive proteolysis mediated by the elastin-degrading enzymes MMP2, MMP9, and MMP12 from the MMP family, and by neutrophil elastase from the serine proteinase family." (PMID 15526056, 2004). "On the other hand, a study by March used a murine model of cigarette smoke exposure, and although an increase in MMP-2 and MMP-9 activity was observed and emphysema was induced by exposure, NAC treatment failed to mitigate the severity of emphysema." (PMID 38892239, 2024). "M2 profiles in COPD promote the production of proteolytic enzymes, such as MMP9 and MMP12, inducing the activation of mucin-related genes and contributing to lung tissue damage, emphysema, and the development of airway obstruction, while inducing wound repair and inflammation resolution." (PMID 38891820, 2024). "After establishing a clear role for HIV in driving smoking-related emphysema, we next wanted to determine whether HIV increases MMP-9 in the alveolar macrophage." (PMID 36331810, 2023). "In mice, the absence of MMP-9 did not protect them from developing emphysema in response to LPS-induced inflammation." (PMID 36835197, 2023). "Therefore, it is possible that the role of MMP-9 in the pathophysiology of COPD is more complex than previously considered and not only related to the development of emphysema." (PMID 36935521, 2023). "When the upregulating MMP-9 cannot be offset by TIMP-1 abundantly, the degradation of elastin and other extracellular matrix components occurs in the alveolar walls and finally leading to emphysema." (PMID 35936787, 2022). "Mature Neutrophils synthesizes MMP-9 and it contributes to airway obstruction by destroying the structural components of ECM as shown by increased MMPs in Bronchoalveolar lavage fluid (BALF) and plasma of emphysema patients." (PMID 33435568, 2021).